TYR (tyrosinase)
Diseases named in the same sentence as TYR in open-access papers (continued):
Sharing a sentence is not in itself a finding about the gene and the disease.
infection (15 papers, 2012 to 2025). The state of being infected such as from the introduction of a foreign agent such as serum, vaccine, antigenic substance or organism. "For instance, VM1G_01234 is a tyrosinase encoding gene and was highly upregulated during the infection." (PMID 38674600, 2024). "Another mechanism is inhibiting the iNOS and tyrosinase expression or eliminating excessive reactive oxygen species to improve the injury effect of free radicals as well, and they can relieve edema of the tissue and encourage wound healing caused by infection-induced inflammation." (PMID 39511672, 2024). "Some enzymes constitute important virulence factors, such as tyrosinase and laccase, enzymes responsible for the production of melanin, which has an important role in host immune evasion, infection proliferation and drug resistance." (PMID 40520592, 2025). "Some enzymes constitute important virulence factors, such as Tyrosinase and laccase, enzymes responsible for production of melanin which has an important role in host immune evasion, infection proliferation and drug resistance." (PMID 40291681, 2025). "Five tyrosinase genes in M. sextelata were upregulated after infection by P. penicillatus." (PMID 34925269, 2021). "Most of the H. oryzae genes involved in plant cell wall degradation, such as proteins containing Glyco_hydro, peptidase, lipase, tyrosinase, cutinase, cellulase, CBM, and LysM domains, were downregulated during infection." (PMID 27658302, 2016). "Tyrosinase and PKS are involved in the synthesis of melanin, a virulence factor that contributes to fungal survival, adaptability, and infection in many phytopathogenic fungi, including Bipolaris sorokiniana, Verticillium dahliae, Lasiodiplodia gilanensis, and Alternaria alternata." (PMID 38773367, 2024). "In the model using melanocyte tyrosinase as an antigen, tyrosinase−/− thymus was transplanted to thymectomized mice and lack of splenic T cell activity was observed after infection with tyrosinase-bearing recombinant virus." (PMID 34848535, 2021).
neurological disorders (8 papers, 2020 to 2025). "Oxyresveratrol possesses diverse biological and pharmacological activities such as the inhibition of tyrosinase and melanogenesis, antioxidant and anti-inflammatory activities, and protective effects against neurological disorders and digestive ailments." (PMID 34299485, 2021). "The antioxidant activity and the ability to inhibit CNS enzymes such as AChE, MAO, and TYR, could explain the traditional use of J. glutinosa in treating disorders of the nervous system." (PMID 40141177, 2025). "The experimental system was an amperometric biosensor with an oxidase (tyrosinase) and a neural esterase (AChE) co-immobilized on the working electrode of a commercially available SPE array to detect markers of neurological disease." (PMID 34821676, 2021).
genetic disorder (7 papers, 2017 to 2025). "This approach could be essential in the understanding of tyrosinase functions and the search for a cure for inherited diseases using this protein as a target in drug screens and future structural studies." (PMID 32019134, 2020).
cardiovascular diseases (3 papers, 2011 to 2022). "Homocysteine inhibits tyrosinase, an enzyme participating in melanine synthesis and it is a marker for cardiovascular diseases." (PMID 32113676, 2020).
metabolic disorders (3 papers, 2018 to 2025). "Additionally, when tested against a panel of enzymes usually targeted for therapeutic purposes in neurodegenerative and metabolic disorders, all samples were found to be good inhibitors of tyrosinase." (PMID 30587771, 2018).
bacterial infection (1 paper, 2023). "Thus, the inhibition activity of tyrosinase, the key enzyme to catalyze the melanogenesis and/or inhibition of bacterial infection, could decrease melanin production." (PMID 36830230, 2023).
TYR also shares sentences with these, for which no sentence is quoted: freckles (8 papers); Photophobia (5); Griscelli syndrome (4); ischemic stroke (4); Parkinson (4); squamous cell carcinoma (4); Anxiety (3); glioma (3); lung carcinoma (3); metabolic syndrome (3); metastatic tumor (3); anemia (2); autism (2); autosomal recessive ocular albinism (2); Chediak-Higashi syndrome (2); cognitive decline (2); colitis (2); congenital cataract (2); Duchenne muscular dystrophy (2); esophageal squamous cell carcinoma (2); Insulin resistance (2); Menkes disease (2); nevus (2); non-melanoma skin carcinoma (2); renal fibrosis (2); retinal disorder (2); Stroke (2); type 1 diabetes (2); urticaria pigmentosa (2); ablepharon macrostomia syndrome (1).
A further 111 diseases each share a sentence with TYR in 1 paper.